HIF1A (hypoxia inducible factor 1 subunit alpha)
Diseases named in the same sentence as HIF1A in open-access papers (continued):
Sharing a sentence is not in itself a finding about the gene and the disease.
breast cancer (continued). "HIF-1α-regulated TGF-β1 can induce EMT to promote the progression of breast cancer, and induction of EMT via Wnt/β-catenin signaling has been shown to be driven by HIF-1α in prostate and hepatocellular carcinoma." (PMID 36050634, 2022). "The gene set enrichment analysis plot and KEGG plot demonstrate that RBCK1 consumption in MCF-7 breast cancer cells inhibited the HIF1α signaling pathway and positively correlated with the HIF1α signaling pathway." (PMID 36473847, 2022). "In common with other tumors, breast cancer tissues present higher levels of HIF-1α and hypoxia, which correlates with poor prognosis, including early relapse and metastatic disease." (PMID 35626715, 2022). "As overexpressed HIF-1α has been correlated with treatment failures, it is considered to be a potential drug target for breast cancer therapy." (PMID 36080483, 2022). "Similar mechanisms were observed in breast cancer cells during acute hypoxia, however, during prolonged hypoxia, the XBP1s induced an miR-153 expression, and this is a negative regulator of HIF-1α." (PMID 36230792, 2022). "In conclusion, our results indicate that plumbagin exerts anticancer activity on MCF-7 breast cancer cells by blocking HIF-1α expressions at both mRNA and protein levels." (PMID 36080483, 2022). "Nonetheless, very few studies have evaluated the predictive value of HIF-1α in breast cancer in patients receiving neoadjuvant chemotherapy." (PMID 36358811, 2022). "BNIP3 is highly expressed in prostate, lung, endometrial, and breast cancer, and HIF-1α can induce further expression." (PMID 36675706, 2022). "Tamoxifen treatment increases HIF-1α positivity in breast cancers and prevents the downregulation of the HIF-2α expression." (PMID 36139678, 2022). "We analyzed the spatial correlation of SET with the macrophage marker CD68 and the hypoxic zone marker hypoxia-inducible factor 1 subunit alpha (HIF1α) using published spatial transcriptome data from breast cancer patients." (PMID 36224346, 2022). "In pancreatic, colon, and breast cancer, HIF-1α was positively correlated with proliferating cell nuclear antigen." (PMID 36226248, 2022). "In conclusion, we find that even though HIF1α stabilization is activated similarly in basal and luminal breast cancer cells the response to hypoxia differs with distinct patterns of gene regulation." (PMID 36077517, 2022). "We first examined levels of HIF-1α and PD-L1 in the murine breast cancer cell lines 4T1 and E0771 cultured under normoxia." (PMID 35239514, 2022). "For example, HIF-1α regulates MIF secretion in breast cancer cells to promote tumor proliferation, angiogenesis, and metastasis." (PMID 36496973, 2022). "HIF-1α/GPER signaling pathway is also involved in the regulation of VEGF expression in breast cancer cells and CAFs exposed to hypoxia." (PMID 36226050, 2022). "GHET1 is a novel lncRNA that regulates the proliferation of breast cancer cells by decreasing HIF-1α expression by increasing the phosphorylation of LATS2 and YAP in order to inhibit the activation of the developmental Hippo pathway." (PMID 35626715, 2022). "Its overexpression inhibits PDK4 and HIF-1A expression and conducts the breast cancer cells towards the energetic phase and radiosensitivity, respectively." (PMID 36230935, 2022). "Our own unpublished work points to a shift from HIF-1α to HIF-2α signaling as luminal breast cancer cells are subjected to prolonged hypoxia." (PMID 36057753, 2022). "AT-533, a novel Hsp90 inhibitor, is considered a potential candidate for breast cancer treatment, as it inhibits breast cancer growth and angiogenesis by blocking HIF-1α/VEGF/VEGFR-2 signaling pathway." (PMID 36003773, 2022). "In clinically relevant works in the literature, it was found that the expression level of HIF1α is an important indicator of breast cancer recurrence and metastasis." (PMID 36473847, 2022).
breast cancer (continued). "Previous studies have focused on the capacity of estrogen to regulate HIF-1α expression in diverse types of cancer cells including thyroid, ovarian, and breast cancer cells, mainly via the PI3K/AKT signaling cascade." (PMID 35158804, 2022). "The activation of HIF-1α through Nrf2 also enhances the angiogenesis and progression of breast cancer." (PMID 35571115, 2022). "Nonetheless, clinical data on genes expression in breast cancer shows c-Myc overexpression despite the presence of isoform HIF-1α." (PMID 36139678, 2022). "In this study, nuclear HIF-1α staining was performed on breast cancer CTC-derived tumors growing in the brain and mammary gland, respectively." (PMID 36003773, 2022). "Further in-depth investigation of the molecular mechanisms of intracellular regulation of the HIF1α pathway will offer new strategies and ideas for treating breast cancer." (PMID 36473847, 2022). "Hypoxia-induced overexpression of HIF-1α is an essential factor that induces drug resistance in breast cancer." (PMID 36003773, 2022). "GPT2 inhibits PHD2 (proline hydroxylase 2) activity, which is involved in the regulation of hypoxia-inducible factor-1α (HIF-1α) stability by decreasing α-KG levels in breast cancer cells." (PMID 36499136, 2022). "As expected by the oxygen diffusion ability, breast precursor lesions such as ductal carcinoma in situ (DCIS) and early stage breast cancer already present HIF-1α overexpression." (PMID 35626715, 2022). "Increased proportions of breast cancer stem cells can be achieved by dual regulation of HIF-1α/2α and ALKBH5 that induces higher expression and lower degradation levels of NANOG." (PMID 35794625, 2022). "RBCK1 modulates the HIF1α signaling pathway through a post-translational mechanism influencing breast cancer development." (PMID 36473847, 2022). "This is supported by the preferential expression of HIF-1α in peri-necrotic tumor cells in TNBC and BRCA1 mutated breast cancers." (PMID 36230969, 2022). "The exosomal LncRNA BCRT1 is significantly upregulated in breast cancer tissues and positively correlates with tumor growth, metastasis, and poor prognosis in breast cancer patients by functioning through the HIF-1α/lncRNA BCRT1/miR-1303/PTBP3 pathways." (PMID 36233088, 2022). "Using the transgenic mouse models of mammary carcinoma with tumor-specific deletion of HIF1A and HIF2A let to evaluate the effects of HIF modulation on tumor dissemination to multiple distant sites." (PMID 36139678, 2022). "A lot of work has been done to elucidate the regulation of HIF-1α under hypoxic conditions; however, the regulation of O2-independent mechanisms in breast carcinoma remains relatively poorly investigated." (PMID 35236823, 2022). "More specifically, type IV collagen-degrading enzymes MMP-2 and MMP-9 show increased expression through a HIF-1α dependent mechanism in in vitro breast carcinoma cell lines." (PMID 36140753, 2022). "Several studies have shown that HIF-1α regulates the expression of protein-coding genes in breast cancer." (PMID 34054950, 2021). "In bone, the hypoxia inducible factor-1 alpha (HIF1A) has a promoting effect on breast cancer metastasis by upregulating prostaglandin endoperoxide synthase-2 (PTGS2, also known as COX-2)." (PMID 33830428, 2021). "OSM can also activate STAT3 and hypoxia-inducible factor-1 alpha (HIF-1α) in estrogen receptor (E.R.)- breast cancer cells or in ER + breast cancer cells in concert with IL-6." (PMID 34488773, 2021). "PTEN loss occurs in both lung and breast cancers, leading to their progression via the activation of PI3K/Akt signaling, and downstream targets including EMT, GSK-3b, HIF-1a, and so on." (PMID 33670518, 2021). "For example, lncRNA BCRT1, which is transcriptionally regulated by HIF-1α under hypoxic conditions, promoted breast cancer cell proliferation and progression." (PMID 34977036, 2021).
breast cancer (continued). "The cellular functions were assayed and the results indicated that CAFs derived sEVs with low miR-7641 levels suppressed breast cancer cell survival, glycolysis, and stem cell properties via the HIF-1α pathway." (PMID 34238918, 2021). "In both miR526b and miR655 expressing MCF-7 cell lines, the expression of PTEN is reduced and both miRNA regulate the expression of HIF1-α in breast cancer." (PMID 33668160, 2021). "FBP1 has been shown to induce apoptosis in human breast cancer cells by inhibiting HIF-1α/BNIP3-mediated mitophagy." (PMID 34502189, 2021). "Apart from the traditional method for the creation of hypoxic conditions, we also induced hypoxia by adding CoCl2, and confirmed it by expressing HIF-1α in breast cancer cells." (PMID 34055597, 2021). "In breast cancer cells, HIF-1α upregulates the expression of KDM4B and further promotes the progression of breast cancer in association with ERα." (PMID 35186950, 2021). "Further investigation showed that CAFs-derived sEVs with low levels of miR-7641 promotes breast cancer cell glycolysis and HIF-1α was regulated by miR-7641." (PMID 34238918, 2021). "It was demonstrated that HIF-1α expression was increased under hypoxia (1% O2) and decreased in the TG in all breast cancer cell lines for 24 h." (PMID 34830821, 2021). "Using the results from The Cancer Genome Atlas database (TCGA) database, we found C1QBP mRNA levels to increase in breast cancer tissues concomitantly with the increasing levels of HIF-1α." (PMID 33708767, 2021). "For example, a study found that SENP1 can deSUMOylate HIF-1α to enhance HIF-1α stabilization and ultimately promote breast cancer metastasis." (PMID 33968766, 2021). "In our study, we therefore focused on the interplay between MB and HIF-1α and different oxidative-stress inducing agents in the high-MB breast cancer cell line MDA-MB-468." (PMID 34671319, 2021). "TAM-derived lnc-HISLA can stabilize HIF-1α protein to enhance aerobic glycolysis and mediate chemo-resistance of breast cancer cells." (PMID 34760687, 2021). "On the other hand, enforced expression of HIF-1α in breast cancer cells increased the transcriptional activity of HIFAL promoter in a dose-dependent manner." (PMID 33637716, 2021). "The cellular functions including proliferation, metastasis, glycolysis, and stem cell features were assayed and the results indicated that CAFs sEVs with low levels of miR-7641 promoted breast cancer stem cell properties via the HIF-1α pathway." (PMID 34238918, 2021). "The protein expression of TARBP2 and HIF-1α was determined by IHC staining using a tissue microarray of human breast cancer." (PMID 35008634, 2021). "Out of the remaining, 6 discuss the role of potential therapeutics targeting diabetes and breast cancer, while also implicating HIF1-α." (PMID 34225729, 2021). "The expression of DDX3X was found to be correlated with overexpression of HIF-1α in breast cancer, indicating the oncogenic role of DDX3X." (PMID 33393628, 2021). "Published in 2017, a study reported the induction of HIF1 expression by hyperinsulinemia mediated inhibition of HIF1-α ubiquitination, in estrogen receptor positive breast cancer cells derived from breast tumor in T2DM mice." (PMID 34225729, 2021). "It was demonstrated that exosome miR-7641 was an important player in the communication between breast cancer cells and the cellular component of the tumor niche suppressed the breast cancer stem cell population and glycolysis by targeting HIF-1α." (PMID 34238918, 2021). "A recent study has confirmed the shift toward lactate and pyruvate production in CAFs isolated from breast cancer patients compared to normal fibroblasts is due to epigenetic reprogramming of HIF-1α and glycolytic enzymes." (PMID 34202979, 2021). "The protein contents of both MYC and HIF1α were consistently decreased upon the treatment of echinomycin for 24 h in lung and breast cancer cell lines." (PMID 33572152, 2021).
breast cancer (continued). "In this study, the authors demonstrated that hypoxia downregulated AURKA via a HIF-1α dependent mechanism, suggesting that HIF-1α is a negative regulator of AURKA in breast cancer tumours." (PMID 34062959, 2021). "The HIF1-α antisense lncRNA (HIFAL) has been found to specifically upregulate HIF1-α activity in the glycolysis of breast cancer; however, further studies that focus on CRC are warranted." (PMID 34571724, 2021). "Cardamonin impedes the growth of breast cancer, along with a decrease in HIF-1α and its target genes, such as lactate dehydrogenase A (LDHA), in vivo." (PMID 34575983, 2021). "So, circRNF20 promoted the proliferation and Warburg effect in breast cancer cells by ensuring the HIF-1α-mediated expression of HK2 in them." (PMID 33806538, 2021). "We further showed that echinomycin caused degradation of HIF1α and MYC in a variety of cancer types tested here, including lung cancer, breast cancer, lymphoma and leukemia." (PMID 33572152, 2021). "Together, these results suggest that JFK promotes HIF-1α-induced glycolysis thus elevating cellular tolerance to hypoxia in breast cancer." (PMID 34336836, 2021). "The results indicated that miR-7641 involved in regulating breast cancer stemness and glycolysis by the HIF-1α pathway." (PMID 34238918, 2021). "Specific deletion of HIF-1α in myeloid cells in the MMTV-PyMT model of breast cancer leads to increased tumor cell apoptosis, elevated IFN-γ production by TILs, and delayed tumor progression." (PMID 34202979, 2021). "Consistently, endothelial cell-specific deletion of HIF-1α reduces lung metastasis in a genetic model of breast cancer, MMTV-PyMT, and leads to a reduction of circulating tumor cells in mice bearing LLC tumors." (PMID 34202979, 2021). "This process involves the stabilization of HIF-1α, which acts as a transcription factor for several oncogenes in cancer cells, including breast cancer." (PMID 34054950, 2021). "Chiavarina and colleagues reported the dual functions of HIF-1α and demonstrated that the HIF-1α functions as a tumor promoter in cancer-associated fibroblasts, as well as a tumor suppressor in MDA-MB-231 breast cancer cells." (PMID 34207699, 2021). "Tumor-cell-intrinsic HIF-1α is required for mammary tumor growth and lung metastasis in a MMTV-PyMT mouse model." (PMID 35008190, 2021). "Coincided with our results, evidence revealed that FBXW7 ectopic expression diminished cell angiogenesis in breast cancer by blocking the HIF‐1α‐VEGF‐A axis." (PMID 33369138, 2021). "Consistently, analysis of public clinical datasets reveals that the mRNA level of JFK is positively correlated with that of HIF-1α in breast cancer." (PMID 34336836, 2021). "As reported in a variety of studies, HIF-1α overexpression is significantly correlated to adverse outcomes and a poorer survival in breast cancer patients." (PMID 33777815, 2021). "HIF1α accumulation was also reduced in MCF7 breast cancer cells under hypoxia when RAC1 was knocked down." (PMID 33603169, 2021). "In this study, qRT-PCR assays were performed to successfully validate five genes (ERα, PR, HER2, E-Cadherin, and HIF1-α) that can be used to aid in determining mammary cancer subtype and biological characteristics." (PMID 34124226, 2021). "In a more recent publication, the expression of HIF1-α was compared among different breast cancer cell lines that expressed miR526b or miR655." (PMID 33668160, 2021). "Additional findings showed an inhibition of breast cancer cell proliferation due to an induction of mitochondrial fusion, and a positive correlation of MB and HIF-1α signaling and effects on ROS and NO homeostasis in a transcriptomics approach." (PMID 34671319, 2021). "HIF-1α levels increased significantly in breast cancer cells with lentivirus-mediated HIF-1α overexpression." (PMID 34238918, 2021).
breast cancer (continued). "At minimum, these analyses of previously published breast cancer datasets and our own analysis of tissues from 14 breast cancer patients support our identification of the HIF-1α-JFK axis." (PMID 34336836, 2021). "PGK1 promotes the progression and metastasis of BRCA by adjusting the HIF-1α-mediated process of breast cancer epithelial-mesenchymal transition." (PMID 33584825, 2021). "A recent study also demonstrated that HIF-1α signaling selectively enhanced breast cancer cell proliferation in the brain." (PMID 35127500, 2021). "It has been shown that LINK-A interacts with PKT6 and LRRK2 and thereby promotes HIF-1α phosphorylation and protein stabilization under normoxic conditions in breast cancer cells." (PMID 34877935, 2021). "The study for the first time demonstrated that miR-7641 suppressed breast cancer cell stemness by HIF-1α." (PMID 34238918, 2021). "Collectively, these findings indicated that sEVs from CAFs promoted breast cancer stem cell properties and glycolysis via miR-7641/HIF-1α, which was a possible new way for targeting breast cancer." (PMID 34238918, 2021). "In a hypoxic breast cancer model, myeloid HIF-1α was shown to mediate the induction of T cell suppression by the control of arginase-I (ArgI) and inducible NO synthase (iNOS) in macrophages." (PMID 33422072, 2021). "The HIF-1α and GLUT1 genes can be considered good markers for breast cancer diagnostic evaluations in liquid biopsies, since their expression is significantly increased in patients with excellent sensitivity and specificity values." (PMID 33888756, 2021). "Inhibitors of HIF-1α and HIF-2α protein synthesis include 2-methoxyestradiol, which affects protein synthesis in lung cancer cells, and KC7F2, which markedly suppresses the synthesis of HIF-1α in glioma, prostate, and breast cancers." (PMID 33401572, 2021). "In breast cancer cells hypoxia-stabilized HIF1α upregulates the inflammatory protein NOS2 in conditions of nutrient deprivation, and NO promotes tumor cell survival, proliferation, and cell migration and mediates drug resistance." (PMID 33859337, 2021). "Although multiple roles for HIF-1α in mediating breast cancer phenotypes are well-defined, many individual HIF-1α-dependent genes remain to be characterized for their role in breast tumor progression and metastasis in specific breast cancer subtypes." (PMID 35008190, 2021). "We observed some evidence of an association between HIF-1α expression and early recurrence among ER−/TAM− breast cancer patients." (PMID 34736510, 2021). "The treatment with CoCl2 increased the expression levels of HIF-1α protein in a concentration-dependent manner in human breast cancer cells MDA-MB-231 and murine breast cancer cells 4T1." (PMID 33546453, 2021). "Previous study showed that PDGFB promoter was activated in breast cancer cells by HIF1α under hypoxia." (PMID 34470658, 2021). "Cell line specific studies show that Parkin can target HIF-1α for degradation in HeLa and breast cancer cell lines, MEFs and human keloids." (PMID 34439955, 2021). "According to the literature, deletion of HIF‐1α in FAP positive fibroblasts accelerates the growth of breast cancer in transgenic mice." (PMID 33943003, 2021). "HIF-1α overexpression has been reported in breast cancer, and it is attributed to the increased expression of glycolysis-related proteins in breast cancer because HIF-1α overexpression is related to HER-2 positivity and TNBC." (PMID 34552932, 2021). "Increased C-X-C motif receptor 4 (CXCR4) expression is present in breast cancer cells that have metastasized to the bone through hypoxia inducible factor 1 alpha subunit (HIF1A) and TGF-β signaling." (PMID 33672831, 2021). "A detailed global assessment of HIF1α and HIF2α binding sites in MCF7 breast cancer cells, for instance, revealed that many of these sites bound HIF1α and HIF2α equally well, while there were only very few sites that bound HIF2α exclusively." (PMID 33125509, 2021).